IL6 (interleukin 6)
Diseases named in the same sentence as IL6 in open-access papers (continued):
Sharing a sentence is not in itself a finding about the gene and the disease.
acute kidney injury (continued). "IL-6-VEGF-axis-induced glomerular microangiopathy may play a crucial role in developing acute kidney injury in TAFRO syndrome and the anti-IL-6 receptor antibody therapy may be useful for TAFRO syndrome refractory to glucocorticoids." (PMID 31623576, 2019). "Importantly, high levels of circulating IL-6 in patients with acute kidney injury are predictive of an increased mortality rate." (PMID 30871285, 2019). "The IL-6 level is also proven as a predictor of acute kidney injury." (PMID 30400775, 2018). "Likewise, it attenuated the increase in the plasma concentrations of pro-inflammatory cytokines including IL-1β and IL-6 induced by renal failure." (PMID 29774097, 2018). "In septic patients with acute renal failure, SepteX has been shown to decrease plasma concentrations of IL-6 and IL-1 receptor antagonist (IL-1ra), correct immune dysfunction and reduce the need for vasopressor support compared to standard renal replacement therapies." (PMID 25937432, 2015). "All-in-all, our analysis does not point to the cytokines IL6, IFNγ and TNFα, that have classically been associated with low grade inflammation in cardiovascular disease and renal failure." (PMID 22957013, 2012). "• Urine IL-6 may be a useful early biomarker to detect acute kidney injury from acute tubular necrosis." (PMID 20942931, 2010). "Based on our animal data, we hypothesized that IL-6 and IL-8 would be early biomarkers of acute kidney injury." (PMID 19570208, 2009). "In septic patients, elevated LPS levels correlate with both increased IL-6 concentrations and worse severity of acute kidney injury (AKI), and targeted antibacterial therapy (e.g., carbapenems) reduces both bacteremia and cytokine-driven organ damage." (PMID 41521316, 2026). "The IL-6/GATA2/SERPINE1 pathway mediates cellular senescence after acute kidney injury, and inhibiting IL-6 can alleviate AKI-induced cellular senescence, providing an important basis for exploring new therapeutic strategies." (PMID 40007559, 2025). "Quercetin-3-O-glucoside can inhibit the expression of TNF-α, IL-1β and IL-6 and the activation of NF-κB, and simultaneously up-regulate the expression of Nrf-2 and HO-1, and inhibit the inflammation and oxidation to resist the induction of cisplatin of acute kidney injury in mice." (PMID 32748813, 2020). "In the present study, we investigated the association of 12 polymorphisms in six inflammatory-response genes (TNF, IL6, IL10, IL18, NFKB1 and NFKBIA) with risk of acute kidney injury (AKI) in children." (PMID 30429237, 2018). "Moreover, it has been shown that the concentrations of PAF in plasma and urine are significantly increased in patients with acute renal failure during septic shock, accompanying with high levels of the pro-inflammatory cytokines including IL-1β, IL-6, IL-8, and TNF-α." (PMID 29950994, 2018). "For IL-6 we failed to reveal a clear association pattern with renal failure as in the case of sTNF-R1 and hsCRP in either sex; here we estimated similar AUCs as in the case of hsCRP for both sexes, which is also true for the sensitivity and specificity at the optimal cut offs." (PMID 25259714, 2014). "Interleukin-6 (IL-6) is a proinflammatory cytokine that increases early in the serum of patients with acute kidney injury (AKI)." (PMID 20942931, 2010). "Further analysis demonstrated thatthe combination of TNF-α, interleukin 2, interleukin 6, and NGAL hadthe highest predictive value for acute kidney injury (area under the curve =0.93)." (PMID 40961276, 2025). "Acute kidney injury is triggered by the production of harmful free radicals and inflammatory processes, with elevated levels of inflammatory cytokines like TNF-α, IL-6, and IL-1β." (PMID 39093465, 2025). "Release of many cytokines, including IL-1, IL-6, IL-8, IL 10, complement C3/C4, and tumor necrosis factor-α PCT, Leucocytes are characteristic of the inflammation and contribute to postoperative acute kidney injury (AKI)." (PMID 38888547, 2024).
acute kidney injury (continued). "Significantly higher values of PCT, IL-6, and CRP (p < 0.05 for all) were observed in patients who were diagnosed with acute kidney injury (AKI) on admission and in patients who later started continuous renal replacement therapy (CRRT)." (PMID 39457628, 2024). "Similarly, α7nAChR reduced the inflammatory response by modulating NF-κB (p65) and IL-6/JAK2/STAT3/SOCS3 signals in acute kidney injury (AKI) model." (PMID 37429998, 2024). "In a model of cisplatin-induced acute kidney injury, APF significantly reduced the levels of IL-1β, IL-6, TNF-α and MCP-1 by inhibiting the mincle/Syk/NF-κB signaling pathway." (PMID 37362082, 2023). "Previous research showed that this metabolite ameliorated the inflammatory response by decreasing the expression of the cytokines TNF-α and IL-6 in a mouse model of sepsis-induced acute kidney injury (AKI), and this effect was dependent on silent information regulator sirtuin 1 (SIRT1) signaling." (PMID 38067518, 2023). "Common risk factors associated with mortality included older age, severe disease, ICU/ventilator requirements, acute kidney injury (AKI) needing dialysis, CT scan abnormalities, and higher levels of inflammatory markers particularly D-dimer and IL6 levels that correlated directly with mortality." (PMID 35669496, 2022). "Both wave risk factors for mortality included older age, severe disease, ICU/ventilator requirements, acute kidney injury (AKI) needing dialysis, Chest Computerized Tomographic (CT) scan abnormalities, and higher levels of inflammatory markers particularly D-dimer and interleukin-6 levels." (PMID 35669496, 2022). "It was concluded that biomarkers such as IL-6, IL-8, TNF-α, MMP-9 and NGAL are reliable acute kidney injury indicators." (PMID 34571700, 2021). "The levels of IL-6 and TNF-α correlated with the levels of creatinine and urea nitrogen, and were also higher in ARDS patients with acute kidney injury (AKI)." (PMID 34088317, 2021). "HMGB1 and IL-6 plasma levels were higher in patients with a higher Sequential Organ Failure Assessment (SOFA) score (> 10), and the presence of septic shock or acute kidney injury." (PMID 33939645, 2021). "Further reports have shown other predictors of poor outcome such as acute kidney injury, acute hepatic injury, the need for mechanical ventilation, elevated c-reactive protein (CRP), interleukin-6 (IL-6), lymphocyte count, and Procalcitonin levels." (PMID 33028914, 2020). "The interaction between NPs and cytokines was demonstrated by the administration of ANP to rats with acute kidney injury induced by I/R where it inhibited mRNA expression of TNF-α, IL-1β, and IL-6 in the lung and kidney." (PMID 29774097, 2018). "Further, we noticed higher serum level of IL-6 in ESRD patients in comparison to the healthy control group, indicating that increment of IL-6 in ESRD HCV+ patients is probably due to renal failure." (PMID 28487598, 2017). "We have noticed a positive correlation between the biomarkers panel of IL-6, OCN, and FGF-23 and renal failure progression (eGFR) in all CKD groups." (PMID 27667892, 2016). "Increased levels of for example serum IL-6, IL-10, and HMGB-1 were reported in pigs and mice in more severe models of local inflammation such as multiple trauma and acute kidney injury." (PMID 27250718, 2016). "IL-6 levels were associated with prolonged mechanical ventilation only in study subjects with acute kidney injury (P = 0.008 vs. P = 0.9 in those without AKI)." (PMID 19570208, 2009). "Main outcome measures included inflammatory and endothelial biomarkers (IL-6, IL-8, angiopoietin-2, syndecan-1), body fluid composition assessed by bioelectrical impedance, and clinical outcomes, including acute kidney injury (AKI), ICU length of stay (LOS), and ICU mortality." (PMID 41938900, 2026).
acute kidney injury (continued). "In murine sepsis-induced acute kidney injury (AKI), melittin significantly reduced renal cytokine expression (e.g., TNF-α, IL-6), suppressed NF-κB activation, and decreased lipid peroxidation markers such as 4-HNE and MDA, while upregulating Nrf2-HO-1 and other antioxidant pathways." (PMID 41301702, 2025). "In the second wave, one patient with severe disease and cardiogenic shock complicated by renal failure received anti-IL6 after no improvement with IVIG and steroids." (PMID 41291581, 2025). "Similarly, ALA alleviated acute kidney injury (AKI) in CLP rats by inhibiting NF-κB; downregulating proinflammatory cytokines (TNF-α, IL-6, IL-1β), iNOS, and HMGB1 expression in renal tissues; and reducing serum blood urea nitrogen (BUN) and creatinine levels." (PMID 40699721, 2025). "Also, in pathologic conditions like acute kidney injury, β2AR activation reduces inflammation by downregulating TNF-α and IL-6 via cAMP-PKA signaling." (PMID 40573268, 2025). "In the LPS induced acute kidney injury (AKI) model, emodin substantially suppresses the activation of the NF-κB signaling pathway and diminishes the production of inflammatory cytokines, including TNF-α and IL-6." (PMID 41424782, 2025). "IL-6 also plays an important role in SAKI, primarily by regulating the inflammatory response, affecting renal microcirculation, and promoting tubular injury, thereby exacerbating renal failure." (PMID 40166075, 2025). "This renal failure was determined by higher levels of TNF-α, CRP, IL-6, and IL-10." (PMID 36851766, 2023). "Previous studies reported that IL‐6 activates the JAK/STAT signaling pathway which serves as a potential target for early intervention in IR‐induced acute renal failure." (PMID 36117389, 2022). "In the study of acute kidney injury (AKI), as an upstream signal of inflammatory pathways, NF-κB and MAPK were activated by a series of inflammatory responses associated with AKI, leading to the production of large amounts of downstream inflammatory cytokines such as IL-6, TNF-α and IL-1β." (PMID 35744798, 2022). "Mitochondrial damage and release of mtDNA into the cytosol activated cGAS-STING dependent IL-6 production without type I interferon in a model of cisplatin-induced acute kidney injury." (PMID 35967325, 2022). "IGF-I’s effect to markedly decrease the IL-6 expression in inflammation has not been previously reported, except in our previous study on acute kidney injury (AKI)." (PMID 34063554, 2021). "Indeed IL-6 trans-signaling by the recombinant IL-6/sIL-6R fusion protein, Hyper-IL-6 (HIL-6) can strongly upregulate STAT3 phosphorylation in the kidney and largely prevent ROS-mediated acute kidney injury (AKI)." (PMID 34055865, 2021). "In a cisplatin-induced acute kidney injury model, treatment with PLA2 attenuated tissue damage by reducing serum creatinine, blood urea nitrogen, production of pro-inflammatory cytokines, such as IL-6 and TNF-α, and macrophage infiltration." (PMID 26820468, 2016). "Synthesis of proinflammatory cytokines such as interleukin (IL)-1, IL-6 and tumor necrosis factor (TNF)-α, increasing in cell adhesion-molecule expression, development of oxidative stress are just some of the changes that occur during acute kidney injury." (PMID 24681567, 2014). "As IL6 is emerging as a predictive factor for acute kidney injury and adverse post-operative outcomes, the absence of a beneficial effect of EPO on its levels parallels the unchanged incidence of acute kidney injury and mortality." (PMID 23033926, 2012). "However, it’s not known how meprin β modulation of the IL-6 signaling pathway impacts the cellular proliferation in IR-induced acute kidney injury." (PMID 39975921, 2025). "This study evaluated the effect of foot immersion with or without neck cooling on systemic proteins associated with acute kidney injury (NGAL, KIM-1), intestinal enterocyte damage (IFABP), immune activation (sCD14) and systemic inflammation (IL-6, TNF-α, CRP) in older adults." (PMID 41178782, 2025).
acute kidney injury (continued). "Additionally, GAL reduced JAK/STAT3 expression in acute kidney injury (AKI) model through modulation of NF-κB (p65) and IL-6/JAK2/STAT3/SOCS3 signals via α7nAChR and in experimental asthma model, α7nAChR exerted promising effects by inhibiting NF-κB/STAT3/SOCS3 signaling." (PMID 37429998, 2024). "In addition to bacterial presence, high levels of cytokines such as tumour necrosis factor α (TNFα), interleukin-6 (IL-6) and interleukin-1(IL-1) can commonly be detected in cirrhotic patients with SBP, which triggers sepsis syndrome pathways and eventually lead to renal failure." (PMID 38551716, 2024). "In oxalate-induced mouse models of acute kidney injury (AKI), there is evidence of inflammation in ferroptosis, inhibition of the expression of proinflammatory cytokines (including CXCL-2 and IL-6), and neutrophil infiltration." (PMID 35844784, 2022). "Compared with patients treated with antioxidants in the low-interleukin-6 subgroup, those in the high-interleukin-6 subgroup had a lower incidence of acute kidney injury but were not different in terms of acute kidney injury severity or intensive care unit mortality." (PMID 32401970, 2020). "Both diabetic patients with or without kidney failure and non-diabetic patients with renal failure had increased TLR2 and TLR4 mRNA expression in association with increased levels of proinflammatory cytokines (TNF-α, IFN-γ, and IL-6) compared to normal subjects." (PMID 33442388, 2020). "In addition, the role of proinflammatory cytokines in cisplatin-induced acute renal failure has been well documented, and elevation of the proinflammatory cytokines TNF-α and IL-1β as well as that of IL-6 has been demonstrated in humans with acute renal failure." (PMID 24171038, 2013). "Overexpressed PVT1 can enhance the expression of IL-6 and IL-1β in a nonbinding manner by regulating the nuclear factor-κB (NF-κB) pathway, which is considered a critical mechanism in the regulation of immune and inflammatory processes, and ultimately aggravating septic acute kidney injury." (PMID 31304055, 2019). "Similarly, patients who developed acute kidney injury (AKI) requiring CRRT had elevated baseline concentrations of CXCL10 (Δ = 3236, 95% CI 1014–5459), IL-10 (Δ = 48.6, 95% CI 34–63), IL-8 (Δ = 39.9, 95% CI 17.7–62.1) and IL-6 (Δ = 1441, 95% CI 125–2697)." (PMID 40869413, 2025). "IL-12, IL-6, and TNF-α play a nonredundant role in determining the severity of acute kidney injury following IRI." (PMID 30013485, 2018). "Finally, in an LPS-induced acute kidney injury (AKI) model, MLN4924 attenuates renal inflammation by inactivating CRL1 and subsequent NFκB inactivation, leading to reduced production of pro-inflammatory cytokines (TNF-α, IL-6, and IL-1β) upon LPS stimulation in renal tubular cells." (PMID 38434245, 2023).
systemic inflammatory response syndrome (237 papers, 2005 to 2026). SIRS is a serious condition related to systemic inflammation, organ dysfunction, and organ failure. "Elevated levels of IL-6 have been correlated with the severity of inflammation and are considered a marker for systemic inflammatory response syndrome (SIRS), which is often associated with severe pancreatitis." (PMID 39694959, 2024). "This molecule transduces the endotoxin signal, thus leading to the release of cytokines such as tumor necrosis factor-α, interferon-γ, interleukin-1β, interleukin-8, and interleukin-6(IL-6), causing systemic inflammatory response syndrome." (PMID 31387523, 2019). "Excessive IL-6 production has been implicated in the development of systemic inflammatory response syndrome (SIRS) and cytokine release syndrome (CRS) following infection or tissue injury." (PMID 31557985, 2016). "The GBS animal with the greatest degree of fetal lung injury (lung score = 4) also developed preterm labor and had a fetal interleukin-6 (IL-6) level of 11.3 pg/ml, which is diagnostic of the fetal systemic inflammatory response syndrome (FIRS) in humans." (PMID 23056493, 2012). "Accordingly, it has been postulated that CS causes a systemic inflammatory response syndrome (SIRS) by the release of pro-inflammatory mediators like interleukin-6 (IL-6) and tumor necrosis factor alpha (TNF-α)." (PMID 22889197, 2012). "Additional pro-inflammatory cytokines associated with sepsis syndromes were influenced by saeR/S as serum IL-6 and IL-2 concentrations were significantly lower in MW2ΔsaeR/S-infected mice (P<0.01)." (PMID 21603642, 2011). "The GBS animal with the greatest degree of fetal lung injury (lung score = 4) also developed preterm labor and had a fetal IL-6 level of 11.3 pg/ml, which is diagnostic of the fetal systemic inflammatory response syndrome (FIRS) in humans." (PMID 22216148, 2011). "Cytokine levels, especially interleukin-6 (IL-6) and interleukin-8 (IL-8), were associated with postoperative infections and systemic inflammatory response syndrome, which itself was a predictive factor the duration of the hospital stay." (PMID 22078633, 2011). "In severe MPP, the sustained high levels of IL-6 may indicate uncontrolled inflammation, leading to increased lung damage and even a “cytokine storm”-like reaction, causing systemic inflammatory response syndrome." (PMID 41048266, 2025). "Moreover, in this process, dysregulated excess and persistent IL-6 synthesis exert pathological effects on acute systemic inflammatory response syndromes and chronic immune-associated diseases, respectively." (PMID 36285159, 2022). "Additionally, IL-6 is an indicator of systemic inflammatory response syndrome (SIRS) with a close association with the severity and mortality of SIRS." (PMID 34643152, 2021). "However, dysregulated, excessive, and persistent levels of IL-6 cause pathological conditions, including acute systemic inflammatory response syndrome and chronic immune-mediated diseases." (PMID 34326779, 2021). "Contact and interaction of blood with foreign surfaces during cardiopulmonary bypass (CPB) cause systemic inflammatory response syndrome (SIRS) through activation of several humoral cascades including cytokines such as IL-6, IL-8, and Tumor Necrosis Factor-α (TNF-α)." (PMID 26064103, 2015). "IL-6 is generated by monocyte-macrophage cells, T-helper type 2 cells, endothelial cells and numerous other types of cell, and has a close association with the severity and lethality of systemic inflammatory response syndrome and MODS." (PMID 24940421, 2014). "Focussing on the highly increased IL-6 levels in LP and HP offspring 3 h after LPS injection, these piglets appear to be more susceptible to bacterial endotoxin exposure with an increased risk of an acute systemic inflammatory response syndrome." (PMID 23190629, 2012).